BMP7 (bone morphogenetic protein 7)
Diseases named in the same sentence as BMP7 in open-access papers (continued):
Sharing a sentence is not in itself a finding about the gene and the disease.
cancer (continued). "Existing contradictory studies in the cancer BMP-7 niche highlights the importance of drawing conclusions only from comprehensive analyses, rather than assessment of potential role players in isolation, which may obscure or skew the full picture." (PMID 37626268, 2023). "Interestingly, regulatory Axl+cDCs were also described in murine and human carcinomas, and BMP7 densities by carcinoma cells positively correlate with disease severity and progression in patients access several carcinoma entities." (PMID 37539048, 2023). "This molecular phenotype may indicate the increased proliferative potential of OS cell lines and the anti-apoptotic effect of both miR-21 and BMP-7 shown previously in other cancer models." (PMID 36139691, 2022). "Moreover, the role of BMP7 in promoting resistance to various cancer therapies has opened new avenues for cancer treatment on a molecular basis." (PMID 36353620, 2022). "Bone morphogenetic protein 7 (BMP7)—one of the members of the BMP family of signaling molecules—is implicated in various types of cancer, influencing the proliferation, migration, and invasion of cancer cells." (PMID 35205840, 2022). "However, some amplified genes in treated HEK293T (e.g., BMP7, MRGBP, CDH12) are associated with EMT in PDAC and other cancer types." (PMID 36289850, 2022). "Mechanistically, BMP-7 suppresses cancer cell invasion by inhibiting TGF-β-induced Integrin β3." (PMID 34063254, 2021). "Collectively, our results suggest that targeting BMP7 may represent a therapeutic approach to overcome resistance to checkpoint blockade therapies in cancer." (PMID 32973129, 2020). "Collectively, these findings suggest that BMP7 inhibition may represent a target for overcoming resistance to cancer immunotherapies." (PMID 32973129, 2020). "The maintenance of telomeres by telomerase in cancer is therefore likely to be reprogrammable by a defined extracellular environment, probably by a combination of extracellular factors with BMP7 to be an inhibitory cytokine of telomerase-mediated telomere homeostasis." (PMID 27696331, 2017). "In addition, we demonstrate the mechanisms whereby BMP7 induces cancer cell death that involve the repression of the hTERT gene and subsequent inhibition of telomerase activity and shortening of telomeres." (PMID 27696331, 2017). "In addition to targeting CCND3, hsa-miR-16-5p is also known to regulate the expression of various angiogenic (e.g., PTGS2, VEGF, FGFR) and/or carcinogenic factors (e.g. EGFR, BMP7, MAPKs) with key roles in cancer/disease signaling pathways." (PMID 26930275, 2016). "In our patient cohort, nine of 11 malignant tumors (82%) had high BMP7 expression." (PMID 26337467, 2015). "In addition, BMP-2, BMP-4, and BMP-7 are frequently overexpressed in various cancers including breast and prostate." (PMID 22514712, 2012). "These included Bmp7, Pparg and Igf2, all of which play an important role in cancer biology." (PMID 21464922, 2011). "Recent studies have demonstrated the clinical impact of BMP-7 expression in various human cancers." (PMID 21224856, 2011). "Interestingly, although Bmp7 is highly expressed in PyMT basal cells as in development, Inhba mRNA is not enriched in PyMT luminal cells; rather, it is more enriched in basal cells, suggesting that gene expression is deregulated in the luminal cancer subtype." (PMID 38708713, 2024). "Next, we sought to test whether Bmp7 functions in the luminal cancer subtype." (PMID 38708713, 2024). "Moreover, both Bmp7 and Inhba are expressed throughout the cancer progression stages examined." (PMID 38708713, 2024). "Furthermore, through expression of ligands for Notch and Bmp7, tuft cells could target Notch1/3 and Endoglin (Eng) on endothelial and smooth muscle cells to promote cancer progression through promotion of angiogenesis." (PMID 37386128, 2023). "Indeed, more comprehensive studies have indicated a beneficial role for BMP-7 in cancer." (PMID 37626268, 2023).
cancer (continued). "In addition, the downregulation of SMAD 1/5/9 was observed in carcinoma tissues, indicating that the BMP7/SMAD signaling pathway may act as a self-defense mechanism against carcinogenesis and the progression of HCC." (PMID 37446238, 2023). "Therefore, the here observed BMP7-driven Axl+cDC2 accumulation in the enlarged psoriatic skin might be of relevance for DC-mediated carcinoma immune evasion." (PMID 37539048, 2023). "The functional operation of an ALK2-SMAD1/5-SMAD4-RUNX3 axis activated, i.e., by BMP7, which counteracts the canonical ALK5-SMAD2/3-SMAD4 signaling, may underly the opposing roles and potential antagonistic mechanisms between the BMP7 and TGFβ pathways in cancer." (PMID 36289908, 2022). "Thus, we identify the BMP7 signaling pathway as a potential immunotherapeutic target in cancer." (PMID 32973129, 2020). "Thus, BMP7 may induce cancer cell ageing and death with a series of molecular and cellular events including telomerase inhibition, telomere shortening, and telomere-associated DNA damage response." (PMID 27696331, 2017). "This distance was significantly reduced in the cancerous region, suggesting that BMP7-positive cancer cells and ACVR1-positive stromal cells interacted within the stromal area near the advanced cancer invasion front." (PMID 40745121, 2025). "Using single-cell analysis, we investigated cancer-fibroblast crosstalk, with emphasis on activin receptor type I (ACVR1) in fibroblasts and bone morphogenetic protein 7 (BMP7) in cancer cells as potential therapeutic targets." (PMID 40745121, 2025). "Together, the data thus confirm that both BMP7 and INHBA are expressed in different cancer subtypes and are likely to play a role in their progression." (PMID 38708713, 2024). "In the cancer context, the TGF-β opposing activity of BMP-7 is again highlighted as major contributor to beneficial outcome, e.g. by inhibiting TGF-β-driven development of invasive cancer via downregulation of integrin β3 expression." (PMID 37626268, 2023). "When queried for the three most common BMP ligands: BMP2, 4 and 7, we observe that basal cancers have upregulation of BMP2 and BMP7 and downregulation of BMP4." (PMID 26274893, 2015). "Gene expression profiling analysis identified SPP1, CTHRC1and GREM1 as potential biomarkers for early diagnosis of the cancer, and SPINK1 and BMP7 to distinguish between AC and SCC in small biopsies or in blood samples." (PMID 24299561, 2013). "For this reason, we stimulated EMTimage with BMP4 or BMP7 during the 4‐day period, in order to evaluate two different members of the BMP family that have distinct biological effects in development and in cancer." (PMID 35348275, 2022). "Whereas the cancer epithelial cell-enriched proteins were characterized of proliferation feature, such as hepatoma-derived growth factor (HDGF), bone morphogenetic protein 7 (BMP7) and tumor protein D52." (PMID 26338966, 2015). "Gremlin-1 binding to cancer cells was unaffected by the presence of BMP-2, BMP-4, and BMP-7." (PMID 22514712, 2012). "Together, these data show that, consistent with its role in development, Bmp7 promotes the progression of triple‐negative breast cancer, and that targeting Bmp7, as a part of the interaction loop, is an effective strategy in treating this cancer subtype." (PMID 38708713, 2024). "Additionally, CS has proven to be a safe and cost-effective delivery system for proteins including stromal cell-derived factor-1α (SDF-1α), fibroblast growth factor (FGF), bone morphogenetic protein-7 (BMP-7) as well as genetic materials and anti-cancer agents." (PMID 36830575, 2023). "Therefore, to test if overexpression of BMP7 can promote a T cell-cold state, we exogenously expressed BMP7 in murine 4T1-S (breast) and MC38 (colon) cancer cells (both of which lack endogenous BMP7 expression) and studied the in vivo effects of BMP7 on intratumoral CD8+ T cell abundance." (PMID 32117236, 2020).
cancer (continued). "However, in the case of BMP-7, a large body of literature in the cancer niche suggests that BMP-7 administration is unlikely to carry significant risk of causing cancer, especially when administered in conditions known to exhibit deficient endogenous BMP-7 levels, such as LN." (PMID 37626268, 2023). "BMP-7 and MMP-9 expression in DU 145 and MDA-MB-231 cells were investigated at early and late time points by Western blot analyses in order to determine whether ESE-16 in combination with 4 Gy radiation affects the invasive and migratory signaling properties in cancer cells." (PMID 34440874, 2021). "BMP7 expression was limited to the apical part and absent in the LGR5+ stem cells located at the very base of the cancer gland." (PMID 31591478, 2020). "Knocking down or neutralizing BMP7 and re-administering anti-PD1 therapy re-sensitized non-small cell lung tumor models to immunotherapy, presenting a novel treatment strategy for overcoming resistance to cancer immunotherapies." (PMID 36353620, 2022). "However, since these studies failed to include assessments of molecules with opposing actions to that of BMP-7, such as TGF-β, these observations may simply suggest a BMP-7 counter-response, rather than a primary driver of cancer pathology." (PMID 37626268, 2023).
kidney disease (23 papers, 2009 to 2025). "This is consistent with previous reports from our laboratory where a low expression of WT-1 in neonatal rats with kidney disease was associated with glomerular changes and reduced nephrogenic markers such as Snail, BMP-7 and E-cadherin." (PMID 27009470, 2016). "Our results were in agreement with previous discoveries demonstrating that lower levels of serum BMP-7 levels are associated with the progression of kidney disease and kidney fibrosis." (PMID 25790348, 2015). "Thus, progression of kidney fibrosis is associated with a concomitant loss of BMP-7 expression in later stages of kidney disease." (PMID 21080950, 2010). "In kidney disease in general, BMP-7 has been named as an anti-fibrotic prevention strategy in multiple contexts." (PMID 37626268, 2023). "In various kidney diseases tubular epithelial expression of BMP7 is decreased and treatment with exogenous BMP7 stimulates kidney repair and prevents progression of kidney disease." (PMID 34061900, 2021). "In the context of chronic kidney disease, the negative regulation of TGF-β/Smad signaling by BMP7 has been shown to be involved in various nephropathies." (PMID 28620300, 2017). "In a previous project we were able to show increased expression of BMP7 mRNA and protein in renal tubule cells in biopsies from proteinuric renal diseases as compared to controls." (PMID 25540021, 2014). "Treatment of kidney disease would require systemic administration of BMP-7, and in this regard, the short serum half-life of the growth factor of about 30 min is a problem." (PMID 20698955, 2010). "In this regard, it has been shown that exogenous administration of pharmacological doses of BMP7 reversed renal disease in several models of experimental renal disease in rodents." (PMID 19696925, 2009). "During various renal diseases epithelial expression of BMP7 is lost." (PMID 29304096, 2018). "Addition of exogenous BMP-7 can both prevent and even reverse fibrosis in models of kidney disease." (PMID 28769795, 2017). "Published studies of BMP-7 as a therapeutic tool in animal models of kidney disease." (PMID 25954203, 2015). "Published studies of BMP-7 as a therapeutic tool in different cell types of kidney disease." (PMID 25954203, 2015). "In addition, BMP-7 improved kidney morphology and renal function in Col4A3 knockout mice that recapitulate Alport Syndrome, a genetic kidney disease." (PMID 25954203, 2015). "Stryker Biotech is currently developing BMP-7-based treatments for kidney disease." (PMID 20698955, 2010). "In addition, since TGFβ is considered the major pro-fibrotic agent in renal disease and since exogenous administration of BMP7 is reported to antagonize the TGFβ-induced phenotype changes in kidney, we have screened the expressions of several genes belonging in the TGFβ/BMP superfamily." (PMID 19696925, 2009). "Saikosaponins have also been shown to attenuate fibrosis in kidney disease by regulating the Hedgehog and transforming growth factor (TGF)-β1/BMP7/Gremlin1/Smad pathways." (PMID 41585876, 2025). "Administration of exogenous BMP7 or reactivation of BMP signalling stimulates renal repair and prevents progression of renal disease." (PMID 29304096, 2018). "Serum BMP-7 and SWV were significantly and progressively decreased and increased, respectively, during the development of renal disease, from the normo- to the micro- and to the macro- groups (all P < 0.01 between each other for BMP-7 and SWV)." (PMID 25790348, 2015). "It has been reported that bone morphogenetic protein 7 (BMP7) and AMP-activated kinase (AMPK) could regulate the signal pathway of the development of BAT, which also play a key role in the kidney disorders." (PMID 32090125, 2020). "BMP7 comprises manifold functions during kidney development and kidney disease but no described pro- or anti-pancreatic effect." (PMID 32825270, 2020). "A BMP7 mimetic, AA123, demonstrated anti-fibrotic effects in a mouse model of kidney disease." (PMID 28769795, 2017).
kidney disease (continued). "Despite these facts, BMP-7 is not being implemented as therapy in the context of renal disease." (PMID 37626268, 2023).
infection (9 papers, 2014 to 2023). The state of being infected such as from the introduction of a foreign agent such as serum, vaccine, antigenic substance or organism. "Between 7 and 14 days of infection, nociceptor-ablated mice showed greater upregulation of Dbp and Bmp7, whereas control mice showed greater upregulation of Lrp5." (PMID 37845223, 2023). "The qualitative and quantitative ALP staining results showed that BMP7 overexpression increased ALP activity in an infection rate-dependent manner." (PMID 33162794, 2020). "Concomitantly, with a reduction of Bmp7 expression, we observed a significant decrease in primary cell viability upon infection with shBmp7-vector (35%–45% reduction versus control GFP-vector)." (PMID 26337467, 2015). "We noted significantly elevated BMP-7 levels in both lavage fluids (P < 0.01, infection 3.2 × 10−8 ± 3.0 × 10−8, control 1.8 × 10−11 ± 4.0 × 10−11) from infected joints and in vitro." (PMID 24877141, 2014). "However, our analysis showed that the increased healing rate, reduced repair time and post-operative infection rates were more prominent after the application of rhBMP-2 compared to rh-BMP-7." (PMID 35807186, 2022). "Interestingly, the high level of ALK2CA expressed was downregulated only in the presence of BMP7 signaling and LSM infection." (PMID 26701726, 2016). "Because these cells were difficult to transfect, we generated lentiviral vectors expressing small hairpin (sh)RNA molecules directed against both mouse and rat Bmp7 gene together with the green fluorescent protein (GFP) to monitor infection efficiency (around 80%–90%, data not shown)." (PMID 26337467, 2015).
neurological disease (4 papers, 2014 to 2023). "We found that rAAV-delivered BMP7 exerted neuroprotective properties in vitro and in vivo suggesting that this might represent a new approach for long-term administration of BMP7 in neurological diseases." (PMID 24618040, 2014). "Bone morphogenetic protein 7 (BMP7) belongs to the transforming growth factor-β (TGF-β) superfamily and plays a neuroprotective role in many different models of neurological disease." (PMID 37875834, 2023).
cardiovascular diseases (3 papers, 2013 to 2021). "In recent years, the use of BMP-7 has been extended to several other inflammatory diseases, including cardiovascular diseases (CVD) and cellular plasticity to neurological disorders." (PMID 31979268, 2020). "BMP7, an inhibitor of apoptosis, fibrosis, and calcification, has been shown to stimulate the differentiation from pro-inflammatory infiltrated monocytes to anti-inflammatory M2 macrophages and reduce the progression of cardiac dysfunction in multiple cardiovascular diseases." (PMID 34781940, 2021). "Therefore, this review focuses on the molecular mechanisms of BMP-7 treatment in cardiovascular disease and its role as an anti-fibrotic, anti-apoptotic and anti-inflammatory growth factor, which emphasizes its potential therapeutic significance in heart diseases." (PMID 31979268, 2020).
genetic disorders (1 paper, 2023). "At least under experimental conditions, not only BMP7 but also activin A can activate pathological osteogenic signaling via mutated ALK2 associated with rare genetic disorders, such as FOP and DIPG32,33." (PMID 37231012, 2023). "Other mutated ALK2 proteins involved in the genetic disorders FOP and DIPG (Q207E, R258G, G328E, and G356D), unique to FOP (R258S and G325A), and unique to DIPG (G328V) also formed the ICD complexes in a few minutes in response to both BMP7 and activin A." (PMID 37231012, 2023).
Heart Diseases (1 paper, 2020). "The novel and most interesting role of BMP-7 is its ability to promote the differentiation of infiltrated pro-inflammatory monocytes into anti-inflammatory M2 macrophages in different cardiac diseases." (PMID 31979268, 2020). "Therefore, a new significant research avenue remains to be explored to understand the cell protective role of BMP-7 in treating heart diseases." (PMID 31979268, 2020). "In conclusion, these studies support that BMP-7 is an effective growth factor that has the potential to inhibit apoptosis, fibrosis and acts as an anti-calcifying agent, which ultimately improves cardiac function in different heart diseases, as summarized in this review." (PMID 31979268, 2020).
musculoskeletal diseases (1 paper, 2021). "Bone morphogenetic protein-7 (BMP-7) has been reported to promote bone healing in spinal fusion, fracture repair, and distraction osteogenesis in animals and humans, and it has been approved by the Food and Drug Administration for adjuvant treatment of various clinical musculoskeletal diseases." (PMID 34447439, 2021).
neurodegenerative disease (1 paper, 2021). A disorder of the central nervous system characterized by gradual and progressive loss of neural tissue and neurologic function. "However, given the fact that Bmp7 is also recognized as a cytokine with pleiotropic functions being offered as a treatment for cardiovascular, fibrotic, metabolic and neurodegenerative diseases, systematic administration of Bmp7 could bring unexpected side effects." (PMID 34863187, 2021).
BMP7 also shares sentences with these, for which no sentence is quoted: kidney (5 papers); adenocarcinoma (2); Alzheimer disease (2); chronic hepatitis (2); COVID-19 (2); Glomerular sclerosis (2); hyperlipidemia (2); hyperphosphatemia (2); injury (2); kidney cancer (2); prostate adenocarcinoma (2); Renal Failure (2); Alport syndrome (1); amyloidosis (1); anaemia (1); ankylosing spondylitis (1); apical periodontitis (1); astrocytic tumor (1); babesiosis (1); biliary atresia (1); bone disorder (1); brain disorder (1); brain tumor (1); carcinoid tumor (1); cataract (1); Chorioretinal coloboma (1); chronic hepatitis B (1); chronic hepatitis C (1); cognitive decline (1); Cognitive impairment (1).
A further 47 diseases each share a sentence with BMP7 in 1 paper.